GAST (gastrin)
Diseases named in the same sentence as GAST in open-access papers (continued):
Sharing a sentence is not in itself a finding about the gene and the disease.
tumor (continued). "Extensive investigations have demonstrated the expression of gastrin, CCK, and their receptors in a variety of tumor cells and tissues and their involvement in the regulation of cell proliferation and apoptosis, as well as the pathogenesis of cancer." (PMID 32210918, 2020). "Among them, more research has been conducted on the anti-cisplatin effect of GAST, and GNRH1 and STC1 can activate the c-Jun N-terminal kinase (JNK) pathway to facilitate tumor development." (PMID 33330624, 2020). "Histological analysis using 10 CCA tumor tissues identified elevated expression levels of CCK-BR and gastrin precursors in CCA tumors, indicating local gastrin production and signaling activation in CCA tumors." (PMID 32069926, 2020). "Based on a large amount of experimental data, tumorigenesis is mediated by gastrin’s effects on the CCK2R-receptor on ECL-cells that in turn leads to hyperplasia, dysplasia, and finally neoplasia." (PMID 31963924, 2020). "The target cell of gastrin, the ECL cell, develops into neoplasia when exposed to long-term hypergastrinemia in all species examined adequately." (PMID 33266504, 2020). "In our mouse orthotopic model, a combination of a PPI, gastrin, and CPE was shown to promote tumor growth and metastasis." (PMID 32485921, 2020). "These tumors may secrete excessive quantities of hormone such as gastrin, insulin, vasoactive intestinal polypeptide (VIP), glucagon, or somatostatin and may be associated with distinct clinical syndromes, with approximately one third of these neoplasms becoming clinically apparent." (PMID 31263451, 2019). "The results showed that the tumor volume and weight were significantly decreased and the tumor tissue p-ERK, P65, and p-P65 levels were increased in the PGC PDX mice after gastrin treatment, compared with the vehicle control group." (PMID 29866191, 2018). "Co-treatment of mice with gastrin and PD98059, PN, or miR23a/27a/24 inhibitors resulted significant decreases in the tumor volumes, compared with the vehicle control groups." (PMID 29866191, 2018). "Natural CCKBR ligands gastrin and CCK, as well as CCKBR antagonists, have been attached to nanocarriers, radionuclides, and imaging agents to improve their uptake by tumor cells." (PMID 27754762, 2017). "The levels of tumor markers (e.g., chromogranin, 5-HIAA, gastrin, and others) pretreatment will be compared with the post-treatment levels (collected every three months) as a measure of the tumor response." (PMID 28629161, 2017). "Dysregulation of β-catenin and other Wnt components lead to nuclear localization of β-catenin, activation of Wnt target genes, including c-Myc, cyclin D1, cyclooxygenase-2, matrix metalloproteinase-7, gastrin, and ITF-2 and enhance tumor formation." (PMID 23646150, 2013). "Annotations of the genes reveal that the majority of the novel gastrin- and HGF-responsive genes seem to participate in processes relevant in the context of tumour biology." (PMID 15846300, 2005). "Unlike in stomach G cells, tumor cells produce progastrin but do not process it into mature gastrin." (PMID 40598473, 2025). "In summary, gastrin showed positive staining in approximately 5% of tumor cells in two NEC cases, but in none of the NET G3 cases." (PMID 41450443, 2025). "Laboratory tests showed that blood glucose, insulin and gastrin levels were normal, and the pNET was considered non-functional; however, the tumor was resected due to its large size." (PMID 40421248, 2025). "Additional tumor markers, including serotonin and gastrin, were within normal limits, suggesting a non-functional tumor." (PMID 39685871, 2024). "Upon immunohistochemical analysis (IHC), tumor cells stained positively for secretin, glicentin, gastrin, and somatostatin, albeit the latter was not ubiquitously expressed among the cells." (PMID 39649120, 2024). "The over-expression of gastrin and gastrin receptors(CCKBR) and cyclooxygenase-2(COX-2) may stimulate tumor growth, angiogenesis, and reduce apoptosis." (PMID 39434880, 2024).
tumor (continued). "The trophic effect of gastrin, which is thought to cause NECH, is not the only factor that increases tumor growth." (PMID 38454240, 2024). "In this current investigation, we showed that treatment of mice with a CCK-BR antagonist, proglumide, could inhibit RIL-175 tumor growth, implying that this drug is blocking the actions of endogenous CCK or gastrin at the receptor." (PMID 36835036, 2023). "Second, our study lacked serum pepsinogen (PG), serum gastrin-17 (gastrin-17, G-17), Hp infection detection, tumor markers, preoperative imaging, and related ESD or EMR treatment data." (PMID 37007147, 2023). "Remarkably, there were no tumor emboli found in tissue sections from the mice treated with the GAST siRNA-loaded NP." (PMID 36614194, 2023). "A unique feature observed in this study was the histologic absence of tumor emboli noted in the mice treated with the GAST siRNA loaded NP, while present in the mice treated with the other loaded NPs." (PMID 36614194, 2023). "By contrast, type III g-NENs are sporadic tumours, and gastrin is not thought to be involved in their pathogenesis." (PMID 35059996, 2022). "One study examined acid secretory changes in 20 sporadic ZES post curative resection (normal fasting serum gastrin, negative secretin provocative test, no imageable tumor)." (PMID 31623145, 2019). "Gastrin exerts tropic effects in the stomach, especially on enterochromaffin-like (ECL) cells, and concerns have also been raised regarding the potential progression to dysplasia or tumor formation following long-term therapy." (PMID 31684070, 2019). "The results showed that the tumor volume and weight were significantly inhibited, p-ERK, P65, p-P65, miR-23a, miR-27a, and miR-24 levels in tumor tissues were significantly increased in mice after treatment with gastrin, LPS, BA, and miRNA mimics." (PMID 29866191, 2018). "Tumor-like lesions in the duodenum were diagnosed as hyperplastic Brunner’s glands, and immunohistological staining with anti-gastrin serum did not reveal any microgastrinomas in the duodenum." (PMID 29181825, 2017). "For the truncated gastrin radiotracer [111In-DOTA]MG11, this method led to impressive in vivo stabilization, which translated into remarkably increased uptake in CCK2R-positive tumors in mice and into high tumor-to-kidney ratios." (PMID 26882895, 2016). "Taken together these data suggest that gastrin peptides synthesized by tumor cells reduces the number of M2 macrophages, without affecting the total macrophage number." (PMID 24901518, 2014). "It was thought that gastric mucosal condition seldom affected the metachronous tumor incidence because serum gastrin and pepsinogen levels did not affect the incidence." (PMID 24672541, 2014). "Here we review the literature on the effects of gastrin:CCKBR signaling on various processes in stroma, and develop the idea that pancreatic stellate cells (PSCs) and tumor infiltrating macrophages (TIMs) may be important players in mediating such effects." (PMID 25346875, 2013). "However, evidence is also accumulating for paracrine growth effects of gastrin, where for example blockade of CCKBR signaling has been shown to reduce tumor fibrosis and inflammation." (PMID 25346875, 2013). "We assessed a range of potential tumour biomarkers, because there is no published evidence about the effect of a gastrin/CCK-2 receptor antagonist on gene expression in humans, and we wanted to prepare for future studies." (PMID 24098507, 2013). "The endocrine cells in the appendix and caecum tumour samples were bombesin-, endorphin-, gastrin- and secretin-negative." (PMID 18252007, 2008). "The one tumor that was negative for gastrin was also completely negative for all hormones." (PMID 40553402, 2025).
tumor (continued). "Upregulated neuropeptide genes, such as PTHLH, Gastrin (GAST), Secretogranin V (SCG5), Neuromedin B (NMB), and Apelin (APLN), were positively correlated with upregulated neurotrophic factors, which were consistent with their roles in tumor progression and neuroimmune crosstalk." (PMID 40805163, 2025). "Tumour markers, including chromogranin A and serum gastrin, could not be assessed due to unavailability." (PMID 41169289, 2025). "In tumor cells, progastrin is not maturated into gastrin but is released from the cells." (PMID 38672239, 2024). "The lack of tumor emboli in this treatment group may in part explain why fewer metastases occurred in GAST siRNA-NP treated mice." (PMID 36614194, 2023). "However, in Goetze's report, gastrin mRNA levels were not compared with the surrounding tissues free of tumor cells and metastatic lymph nodes." (PMID 34976177, 2022). "Case 3, non-functioning tumor, was negative for four pancreatic hormones and gastrin." (PMID 32020844, 2020). "Indeed, gastrin and CCK, as well as their receptors, are expressed in a variety of tumor cell lines, animal models, and human samples, and might contribute to certain carcinogenesis." (PMID 32210918, 2020). "Metastatic tumor masses along with the production of peptide hormones, such as gastrin, somatostatin, insulin, glucagon, or vaso inhibitory peptide (VIP) by tumor cells, may lead to severe symptoms and complications, such as diarrhoea, gastric ulcers, flush, diabetes, or hypoglycaemia." (PMID 31527438, 2019). "In addition, it is possible that gastrin peptides on the NP surface could activate the CCKBR, stimulating the proliferation of tumor cells." (PMID 27754762, 2017). "Gastrin plays an important role in the development of multiple tumors and induces FAK and paxillin phosphorylation, suggesting that this might be a factor of tumor pathogenesis." (PMID 24885567, 2014). "Six months later, serum gastrin was still elevated despite lack of recurrence of tumor." (PMID 23432909, 2013). "We report that CCK2R- and gastrin mRNA co-expression may play a role in a portion, but not in all of these tumours, and that aberrant splicing takes places in these tissues generating multiple forms of 3'-end variant CCK2R mRNAs." (PMID 21504585, 2011). "After tumor resection, the plasma gastrin level did not change." (PMID 20825631, 2010). "Several studies based on clinical observation or animal models of hypergastrinemia have shown that gastrin promoted tumor growth, and there is no precise assessment of how gastrin contributes to GC progression in humans.Whether and how gastrin affects GC cells remains controversial." (PMID 29866191, 2018). "The posterior mediastinal tumor was examined only by biopsy and was diagnosed as NET G2, and was positive for CgA and serotonin but negative for gastrin." (PMID 37867522, 2023). "Our study results were not supportive of a positive correlation between gastrin serum levels and the TNM stage of the tumor, as proposed in some published studies." (PMID 22719803, 2012). "Immunohistyochemically, tumor cells were positive for cytokeratin, synaptophysin, neuron-specific enolase, and CD56; they were negative for chromogranin, gastrin, glucagon, somatostatin, pancreatic polypeptide, and vasoactive intestinal polypeptide." (PMID 27990210, 2009). "These tumours occur in patients without hypergastrinemia but taking into consideration that the ECL cell has a growth-stimulating gastrin receptor, gastrin could nevertheless play a role in tumour development." (PMID 33266504, 2020). "In a selected panel of tumour cell lines (SCLC, non-SCLC, ovarian, colorectal and pancreatic), the expression of the mitogenic neuropeptide receptors for vasopressin, gastrin-releasing peptide (GRP), bradykinin and gastrin was examined, and their sensitivity to SP-G tested in vitro and in vivo." (PMID 12771999, 2003).
cancer (87 papers, 2002 to 2025). A tumor composed of atypical neoplastic, often pleomorphic cells that invade other tissues. "Excessive vasopressin can lead to water retention disorders, and chronically elevated gastrin has been linked to hyperplasia and an increased cancer risk." (PMID 40001527, 2025). "Gastrin-SiO2 microspheres, which cannot be absorbed into the circulation, reduce the risk of inflammation and cancer." (PMID 35674015, 2022). "It is accordingly difficult to conceive that gastrin should predispose to carcinoma developing from the antral mucosa." (PMID 30567376, 2018). "Since the mitochondrial associated protein was overexpressed in gastrin-silenced cells, we hypothesize that there may be some mitochondrial defects in cancer cells." (PMID 33937399, 2021). "In vivo evidence for the role of lactic acid-producing bacteria in gastric carcinogenesis has been the colonization of an Insulin-Gastrin transgenic mouse model with lactic acid-producing microbiota, resulting in gastrointestinal intraepithelial neoplasia and upregulation of cancer-associated genes." (PMID 32650561, 2020). "Overall, our results indicate that CLU could be involved in gastrin-induced pro-survival signaling and remodeling of the oxyntic mucosa; and might therefore influence both gastric homeostasis and cancer risk." (PMID 28902909, 2017). "Whether gastrin is implicated in the ability of cancer cells to metastasize to the lymph nodes merits further research." (PMID 22719803, 2012). "Lower levels of GAST (gastrin) RNA in cancer tissues could help explain the concomitant loss of the gastrin signaling factor CHGA (chromogranin)." (PMID 22929309, 2012). "Additionally, since the bombesin receptors are widely expressed in mammals, the therapeutic potential of BLPs to treat multiple diseases, for instance, cancer cell growth, blood pressure, gastrin release, and pancreatic secretion-associated disorders, are worthwhile to study in the future." (PMID 36250016, 2022). "Polyantibody stimulator (PAS) vaccine that targets gastrin reduces cancer proliferation when administered as monotherapy." (PMID 39003350, 2024). "Another possible mechanism by which PPIs contribute to cancer development is their effect on the hormone gastrin." (PMID 38610738, 2024). "Future studies on post-ESD gastrin levels and cancer prognosis are necessary to refine follow-up strategies." (PMID 39518740, 2024). "Nevertheless, dermal fibroblasts/myofibroblasts, known also to express CCK2R, increased gastrin-induced cancer cell invasion." (PMID 38069171, 2023). "We wanted to validate the efficacy of the GAST siRNA loaded nanoparticle in AsPC-1 cells, a cancer that produces >5 fold more gastrin than PANC-1 cells." (PMID 36614194, 2023). "Gastrin induces migration and invasion in cancer cell lines, at least in part, by activating extracellular proteases of the matrix metalloproteinase (MMP) family." (PMID 38069171, 2023). "hPG80 synthesis is product of overexpression of GAST gene in cancer cells and human circulating progastrin can now be measured accurately with help of DxPG80 Enzyme-Linked Immunosorbent Assay (ELISA) based test." (PMID 35205614, 2022). "In contrast, as a result of GAST gene expression, high hPG80 levels are detected in blood of cancer patients." (PMID 35205614, 2022). "Gastrin is currently considered to be related to cancer development, proliferation, and anti-apoptosis in addition to digestion-related functions." (PMID 36385012, 2022). "The apoptosis rate of the gastrin knockdown cancer cell was significantly increased; meanwhile, gastrin knockdown leads to increase of membrane potential and decrease of intracellular ROS production." (PMID 33937399, 2021). "Gastrin is the major ligand activating the CCK-BR and because PAS therapy induces neutralizing gastrin antibodies and gastrin-activated memory T cells, the ability to decrease signaling at this receptor is central to inhibiting cancer growth." (PMID 34926305, 2021).
cancer (continued). "Another line of evidence, the identification and characterization of the CCK2R splice variants and mutations, further confirmed the involvement of the gastrin and CCK system in cell proliferation and cancer pathogenesis." (PMID 32210918, 2020). "The gastrointestinal (GI) peptide hormone, gastrin, promotes the invasiveness of cancer cells by the induction of MMP-1, -2, and -9 secretion." (PMID 31952344, 2020). "For example, Gastrin, a powerful self-renewal promoter in cancer, is a functionally relevant downstream target of the β-catenin signaling pathway and can further enhance Wnt pathway signaling." (PMID 30275459, 2018). "More interestingly, knockdown of CacyBP/SIP abolished the stimulatory effect of gastrin on the proliferation of these two cancer cells." (PMID 28196083, 2017). "Under normal conditions, gastrin treatment of human cancer cells significantly stimulated proliferation and colony formation, based on MTT and colony formation assays." (PMID 28196083, 2017). "This gave birth to a number of strategies to prevent cancer cell progression by reducing gastrin expression." (PMID 28781948, 2017). "Further development of the resources presented here should be of high interest in translational research aimed at identifying new targets and biomarkers for treatment and diagnostics of gastrin- and/or cholecystokinin-related disease, including cancer." (PMID 26205660, 2015). "Qualitative assessment of the expression of this Wnt ligand indicates that the amount of positive cells decreases as gastrin production in cancer cells increases." (PMID 24901518, 2014). "In a case-control study from Japan, the highest cancer risk (risk ratio 25) was observed in patients with low plasma levels of PGI (or ratio PGI/PGII) and with a concomitantly low amidated gastrin-17." (PMID 22242613, 2012). "The GI peptide hormone gastrin (G17 and its unprocessed forms) can regulate various cellular processes involved in cancer." (PMID 20637111, 2010). "Possible explanations involve changes in the gut microbiome, output of gastrin, the proliferation of enterochromaffin-like cells, and/or non-specific binding to protein targets associated with cancer." (PMID 38610738, 2024). "Moreover, in addition to the fact that GAST is a direct target of the ß-catenin/Tcf4 pathway, activated in many cancers, including HCC, a large body of literature supports the functional role of hPG80 in tumorigenesis." (PMID 35053564, 2022). "Gastrin and its derivatives have long been considered cell growth factors and have been reported to have regulatory effects (such as antiapoptotic and proliferative effects) on some cells (including the gastric epithelium and cancer cells)." (PMID 35126509, 2022). "Likewise, the CCK-BR also becomes over-expressed in cancer cells and this receptor is responsive to both paracrine and autocrine stimulation by gastrin." (PMID 34926305, 2021). "Moreover, in addition to the fact that GAST is a direct target of the ß-catenin/Tcf4 pathway, activated in many cancers, including RCC, a large body of literature supports the functional role of hPG80 in tumorigenesis." (PMID 33498444, 2021). "Although the extraantroduodenal synthesis of gastrin is without significance in the normal adult organism, the phenomenon is interesting from an oncofetal carcinogenetic and hence cancer diagnostic point of view." (PMID 34209478, 2021). "Thus, the ECL cell and its main regulator, gastrin, are central in human gastric carcinogenesis, which make new possibilities in prevention, prophylaxis, and treatment of this cancer." (PMID 33266504, 2020). "Physiologically, two sources of gastrin, originating from mucosal G cells and gastrointestinal tumors, have been suggested to act in different fashions to promote the pathogenesis and development of certain types of cancer." (PMID 32210918, 2020).